NFATC2 (nuclear factor of activated T cells 2)
Diseases named in the same sentence as NFATC2 in open-access papers (continued):
Sharing a sentence is not in itself a finding about the gene and the disease.
COVID-19 (1 paper, 2025). A disease caused by infection with severe acute respiratory syndrome coronavirus 2. "Compared with vehicle, VT-109 also reduced NFATC2 nuclear accumulation in endothelial and immune cells at 7 dpi, suggesting that VT-109 has the potential to alleviate inflammation in COVID-19-induced pneumonia." (PMID 41253746, 2025).
diabetic nephropathy (1 paper, 2022). "As a consequence, NFATC2 may be a new potential biomarker for diabetic nephropathy." (PMID 35885938, 2022). "NFATC2 may be a new potential biomarker of diabetic nephropathy." (PMID 35885938, 2022). "NFATC2, which can indirectly affect the output of PGI2 and related signaling pathways, provides new therapeutic targets for diabetic nephropathy." (PMID 35885938, 2022). "Prognostic analysis and enrichment analysis of ‘dark’ genes show that NFATC2 indirectly affects PGI2 production in VEGF signaling pathway, which has a certain impact on the treatment of diabetic nephropathy and can be used as a potential therapeutic drug target." (PMID 35885938, 2022). "Finally, ‘dark’ genes are identified, and enrichment analysis shows that NFATC2 is involved in the VEGF signaling pathway and indirectly affects the production of Prostacyclin (PGI2), which may be a potential biomarker for diabetic nephropathy." (PMID 35885938, 2022).
Down syndrome (1 paper, 2009). "Two NFATC negative regulators both locate to the Down syndrome critical region of human Chromosome 21, Nfatc2−/− and Nfatc4−/− double-knockout mice have physical and cognitive features resembling human Down syndrome." (PMID 19468298, 2009).
essential thrombocythemia (1 paper, 2014). A chronic myeloproliferative neoplasm that involves primarily the megakaryocytic lineage. "Recently, it was reported that haploinsufficency of NFATC2 contributes to the pathogenesis of essential thrombocythemia with del(20q)." (PMID 25057852, 2014).
gastric adenocarcinoma (1 paper, 2020). "IHC staining results confirmed that the STAT3/MSK1/NFATc2 axis was highly activated in mouse gastric adenocarcinoma samples." (PMID 32041943, 2020).
Glomerular sclerosis (1 paper, 2020). Accumulation of scar tissue within the glomerulus. "It has been shown that NFATC2 podocyte-specific overexpression leads to proteinuria and glomerular sclerosis." (PMID 33015191, 2020).
hepatitis B (1 paper, 2021). "Since Cs-A is a canonical drug recommended by “Asian-Pacific clinical practice guidelines” on the management of hepatitis B, in the future study, we will further investigate whether Cs-A can inhibit the Ct-HBx- NFATC2-TXNIP axis to suppress HCC progression." (PMID 33323975, 2021).
inflammatory bowel disease (1 paper, 2017). A spectrum of small and large bowel inflammatory diseases of unknown etiology. "However, NKX2-3 expression is regulated by transcription factor NFATC2 as identified by single nucleotide polymorphism (SNP)-analyses of patients suffering inflammatory bowel disease." (PMID 28151996, 2017).
lung tumor (1 paper, 2025). "This study introduces a novel salivary and lung tumor entity driven by NFATC2::NUTM2A/B fusions and displaying myoepithelial‐like morphology but imperfect myoepithelial immunophenotype." (PMID 40944358, 2025). "This small series introduces a histologically distinct novel salivary gland and lung tumor entity driven by NFATC2::NUTM2A/B fusions and displaying variable myoepithelial‐like morphology but an imperfect myoepithelial immunophenotype." (PMID 40944358, 2025). "Original diagnoses and immunohistochemical findings in NFATC2::NUTM2A/B fusion salivary gland and lung tumors." (PMID 40944358, 2025).
Lymphadenopathy (1 paper, 2014). Enlargement (swelling) of a lymph node. "Unlike the gross splenomegaly that develops in mixed background Nfatc2 KO mice, congenic B6 Nfatc2 KO mice developed generalized lymphadenopathy that increased in severity with age with only mild or no splenomegaly being observed up to ∼15 months of age." (PMID 24945807, 2014).
mental deficiency (1 paper, 2009). "Dysregulation of NFATC2 in the postnatal nervous system may contribute to mental deficiency in CdLS." (PMID 19468298, 2009).
metastatic cancers (1 paper, 2021). A carcinoma which has spread from the original site of growth to another anatomic site. "Nevertheless, enhanced expression of NFATc2 has been reported in patients with metastatic cancers, invasive cancers, and highly malignant cancers, suggesting that functional changes in NFATc2 may induce angiogenic dysregulation in cancer cells." (PMID 33800389, 2021).
mild cognitive impairment (1 paper, 2015). "In AD brains, various isoforms of NFAT demonstrate differential activation profiles with nuclear fractions of NFAT1 (also known as NFATc2) elevated in patients with mild cognitive impairment (MCI) while nuclear fractions of NFAT3 (NFATc4) are increased in AD patient brains." (PMID 25889879, 2015).
myocardial infarction (1 paper, 2023). Gross necrosis of the myocardium, as a result of interruption of the blood supply to the area, as in coronary thrombosis. "In comparison, in adult mice Nfatc2 does not appear to be significantly upregulated by cardiomyocytes following myocardial infarction, however there is a significant increase in the cardiomyocyte expression of Nppb in infarcted mouse hearts." (PMID 38259319, 2023).
myocarditis (1 paper, 2025). Myocarditis is a condition that is characterized by inflammation of the heart muscle (myocardium). "Myocarditis sera induced CAMTA2, ITGB6, NFATC2, and XDH gene expression significantly (p <0.05) above healthy sera." (PMID 40181955, 2025).
Osteopenia (1 paper, 2025). Osteopenia is a term to define bone density that is not normal but also not as low as osteoporosis. "NFATC2 activation in osteoblasts inhibits bone formation and leads to osteopenia in cancellous bone, and NFATC2 activation also impairs osteoblast generation in vitro." (PMID 40561275, 2025).
pancreas adenocarcinoma (1 paper, 2017). "NFATC2, a transcription factor, when knocked down, increases the apoptosis induced by gemcitabine in PaTu-8988t pancreas adenocarcinoma cells." (PMID 29023490, 2017).
papillary thyroid cancer (1 paper, 2020). "However, their bioinformatics analysis based on gene chips showed that AKT3, nuclear factor of activated T-cells, cytoplasmic 2 (NFATc2), and protein phosphatase 3 catalytic A (PPP3CA) were potential targets of HSDL2 in papillary thyroid cancer." (PMID 32211805, 2020).
salivary gland neoplasm (1 paper, 2025). Tumors of the SALIVARY GLANDS. "We herein describe detailed clinicopathological and molecular features of four neoplasms that are not classifiable into any of the established soft tissue, pulmonary, or salivary gland tumor entities, all carrying a novel NFATC2 fusion." (PMID 40944358, 2025).
soft (1 paper, 2025). "The EWSR1::NFATC2 fusion (case 10) showed an encapsulated soft tissue neoplasm composed of clusters of epithelioid tumor cells forming acinar-like structures, within abundant myxoid stroma." (PMID 39636306, 2025).
soft tissue sarcoma (1 paper, 2022). A malignant neoplasm arising from muscle tissue, adipose tissue, blood vessels, fibrous tissue, or other supportive tissues excluding the bones. "The EWSR1::NFATC2 bone and soft tissue sarcomas presented as slowly growing masses." (PMID 36555836, 2022).
Splenomegaly (1 paper, 2014). Abnormal increased size of the spleen. "Nfatc2 KO mice in a mixed B6×129/SvJ background showed splenomegaly with reduced thresholds for T-cell activation, and these observations were faithfully replicated in our studies of the same mice." (PMID 24945807, 2014).
squamous cell carcinoma (1 paper, 2017). A carcinoma arising from squamous epithelial cells. "To avoid the confounding effect of SOX2 gene amplification in squamous cell carcinoma (SCC), and to focus on tumors with demonstrated involvement of NFATc2, we performed IHC analysis on 92 moderately to poorly differentiated AD." (PMID 28737489, 2017).
submandibular gland tumor (1 paper, 2025). "The one recently reported case (4.2 cm NFATC2::NUTM2B fused submandibular gland tumor in a 68‐year‐old male, reported as carcinoma with myoepithelial features and treated by surgery + adjuvant radiotherapy) had an uneventful course at 20 months follow‐up." (PMID 40944358, 2025).
tauopathy (1 paper, 2022). Neurodegenerative disorders involving deposition of abnormal tau protein isoforms (tau proteins) in neurons and glial cells in the brain. "In a subsequent step, overall feature importance assessment highlighted IER- and cellular immunity-related TFs (FOS, JUN, NFATC2/3, STAT1) as most useful in predicting the tauopathy or Ctrl state." (PMID 35976433, 2022).
tumor (124 papers, 2010 to 2026). "To gain further insight into the behavior of these tumors, we analyzed a spectrum of EWSR1/FUS::NFATC2-rearranged neoplasms and discuss their radiologic, diagnostic, and molecular features in relation to their prognosis." (PMID 36555836, 2022). "To gain further insights into the behavior of these tumors, we analyzed a spectrum of EWSR1/FUS::NFATC2-rearranged neoplasms and discuss their key diagnostic and molecular features in relation to their prognosis." (PMID 36555836, 2022). "The results indicated NFATc2 expression was associated with repressed tumor differentiation and adverse patient survivals." (PMID 28737489, 2017). "Consistent with this, our patient outcome data showed that tumor expression of NFATc2 was associated with significantly better survival." (PMID 26795951, 2016). "We next determined if dual deficiencies of Nfatc2 and Tob1 would exacerbate the parenchymal lymphoid infiltration or accelerate tumor development." (PMID 24945807, 2014). "Moreover, calcineurin/nuclear factor of activated T cells C2 (NFATC2) is implicated in tumor angiogenesis growth and invasion." (PMID 35406721, 2022). "In addition, Nfatc2 deficient T cells also were resistant to tumor-induced clonal anergy in the B16 model." (PMID 24945807, 2014). "Notably, administration of hyper-IL-6 abrogated protection from tumor progression in NFATc2-deficient mice and restored tumor incidence to levels observed in wild-type mice." (PMID 23109839, 2012). "With regard to tumor development, we favor the explanation that Nfatc2 deficiency facilitates development of plasmablastic malignancies similar to those seen in Fasl-deficient (gld) mice and other mice, which might be driven by chronic antigenic stimulation or perhaps by autoantigens." (PMID 24945807, 2014). "Wnt pathway, which is basically related to both MRPS16 and NFATC2, is an important signally pathway in the regulation of tumour proliferation and progression." (PMID 41578162, 2026). "The tumours in the mice inoculated with MRPS16‐OE + NFATC2‐KD U87 cells grew slower than the other two groups, as indicated by the bioluminescence of the tumour, and the overall survival is higher than these two groups." (PMID 41578162, 2026). "We describe four myoepithelial‐like neoplasms of salivary (two) and pulmonary (two) origin, carrying recurrent NFATC2 fusions involving NUTM2B (three) and NUTM2A (one) as fusion partners." (PMID 40944358, 2025). "The myoepithelial‐like morphology of these tumors, their stromal characteristics, and their bland morphology are reminiscent of features seen in some NFATC2::EWSR1/FUS fusion neoplasms of bone and soft tissue." (PMID 40944358, 2025). "In cells transfected with Sh‐NFATc2/Gal9‐OE, tumor sphere formation, and cancer drug resistance were restored compared to those in cells with only NFATc2 knockdown." (PMID 38528665, 2024). "This study unveils the important role of NFATc2/galectin‐9 axis in modulating tumor‐initiating cell (TIC) phenotypes and immune suppression in lung cancer." (PMID 38528665, 2024). "Our study supports and expands previously reported molecular findings of EWSR1/FUS::NFATC2-rearranged neoplasms." (PMID 36555836, 2022). "In our study, we analyzed a biological spectrum of bone and soft tissue EWSR1/FUS::NFATC2-rearranged neoplasms." (PMID 36555836, 2022). "Immunohistochemistry with CD99 and EMA plays a limited role, as both benign and malignant EWSR1/FUS::NFATC2-rearranged neoplasms can stain positive." (PMID 36555836, 2022). "In the last decade, new tumor entities have been described, including EWSR1/FUS::NFATC2-rearranged neoplasms of different biologic behavior." (PMID 36555836, 2022). "When compared to their control counterparts, TRPM7-silenced tumor samples had significantly lower expression of NFATC2, Notch1, and P-MEK proteins." (PMID 35771152, 2022).
tumor (continued). "Among various NFATs, NFATc1 (NFAT2) and NFATc2 (NFAT1) seemed to be essential for the regulation of tumor related functions, including cell survival/proliferation, invasive migration and angiogenesis." (PMID 34187410, 2021). "High level activated NFATc2 expression with widespread nuclear and/or cytoplasmic staining were detected in isolated or small clusters of tumor cells, accompanied by an elevated IL-6 cytoplasmic staining in the corresponding areas." (PMID 32041943, 2020). "On the other hand, NFATc2 and NFATc4 expression was comparable between normal and tumour samples, although with low abundance." (PMID 31249342, 2019). "Our data suggest that NFATc1 and especially NFATc3 are overexpressed in tumour samples compared with normal tissue, while NFATc2 is minimally expressed." (PMID 31249342, 2019). "Functionally, NFATc2/SOX2 coupling contributes to tumor behavior as depletion of SOX2 in cell lines with NFATc2 overexpression led to significant suppression of TIC phenotypes." (PMID 28737489, 2017). "With additional stable NFATc2 knockdown, tumor shrinkage was enhanced to 3.15 and 2.2 fold relative to respective vehicle controls (p<0.01), while tumor growth rate was also retarded." (PMID 28737489, 2017). "In mice with NFATc2 knockdown, tumor regrowth was observed in only 3 and 2 mice of the sh-NFATc2-A and sh-NFATc2-B groups, respectively." (PMID 28737489, 2017). "Using an alternative model, we investigated the effects of NFATc2 inhibition on response to short term gefitinib treatment for 5 days which allowed tumor recovery from the pronounced effect of gefitinib." (PMID 28737489, 2017). "Since NFATc2 is expressed by tumor infiltrating leukocytes, specific conclusions cannot be reached using this approach." (PMID 28737489, 2017). "High NFATc2 expression significantly predicted poor tumor differentiation, advanced tumor stage and TNM stage." (PMID 28737489, 2017). "If NFATc2 supports tumor-initiating phenotypes, it is expected to be expressed at a higher level in TIC compared to non-TIC." (PMID 28737489, 2017). "Subcutaneous xenograft models showed NFATc2 knockdown significantly reduced tumor sizes and retarded growth rates of HCC827 and PDCL#24, respectively." (PMID 28737489, 2017). "In a sarcoma model, NFATc1 was also found to be oncogenic, whereas NFATc2 functioned as a tumor suppressor." (PMID 25638160, 2015). "This in turn provides a potential explanation for the long latency that precedes tumor formation in Nfatc2 KO mice." (PMID 24945807, 2014). "Its pro-apoptotic activity favours, on the other hand, NFATc2 as a tumor suppressor, and it has been described as a suppressor of neoplastic changes in chondrogenesis." (PMID 22764736, 2012). "In in vivo experiments with BABL/c mice inoculated with U251 and U87 cells intracranially, the knockdown of MRPS16 and overexpression of NFATC2 led to the tumours in the mice exhibiting a high growth rate compared with mice inoculated with cells that only had the MRPS16 gene knocked down." (PMID 41578162, 2026). "In summary, we presented four cases (two pulmonary and two salivary) of a distinctive low‐grade neoplasm characterized by bland histology, myoepithelial‐like morphology but with an imperfect myoepithelial immunophenotype, recurrent NFATC2::NUTM2A/B fusions, and likely an indolent clinical behavior." (PMID 40944358, 2025). "Despite the wide implementation of different next‐generation sequencing tools in surgical pathology and in research studies, neoplasms carrying NFATC2::NUTM2A/B fusions have not been reported before, underlining the rarity of these fusions in general." (PMID 40944358, 2025). "Immune responses were enriched in tumours of the psyllium plus inulin group compared to psyllium plus RS, especially the pathways of humoral immunity, cytokines and their receptors, and interferon, along with Bst1 and Nfatc2 gene expression." (PMID 38745230, 2024).